ALB (albumin)
Diseases named in the same sentence as ALB in open-access papers (continued):
Sharing a sentence is not in itself a finding about the gene and the disease.
Cognitive impairment (continued). "Third, frailty was estimated through a simple toolset (Geriatric Status Scale) including only basic daily life activities and cognitive impairment; however, other variables relative to nutritional status (BMI, albumin, hemoglobin) were collected separately." (PMID 36277797, 2022). "Using a fixed-effects model, the predictors of mortality were: the surprise question, performance status, cognitive impairment, (sub)cutaneous metastases, body mass index, comorbidity, serum albumin, and hemoglobin." (PMID 35053493, 2022). "This scoping review has highlighted the relationship between low levels of vitamin B12, vitamin A, omega fatty acid, vitamin D, and albumin and mild cognitive impairment based on published cross-sectional studies." (PMID 36497797, 2022). "The results of our indicate that advanced age, living alone, lower education level, lower levels of ALB and TG, and elevated AST to ALT ratio were associated with cognitive impairment among the elderly." (PMID 36313027, 2022). "Cognitive impairment group exhibits older age, more female sex, lower education level, and lower levels of albumin and triglyceride." (PMID 36313027, 2022). "The living alone (+)/cognitive impairment (+) group was more likely to have a lower serum albumin level." (PMID 35160273, 2022). "Frailty was measured using serum albumin, hemoglobin, gait speed, functional dependence, and cognitive impairment." (PMID 36193709, 2022). "The GNRI is of special interest for patients with potential cognitive impairment, as it only requires weight, height and serum albumin levels, while other indices such as the MNA-SF or MUST often require the completion of a structured questionnaire." (PMID 34070955, 2021). "In vivo studies corroborates in vitro finding as a 3×Tg mouse model treated with human serum albumin exhibit reduced Aβ deposition and ameliorated cognitive impairment." (PMID 34454574, 2021). "As a result, we found that older adults who both lived alone and had cognitive impairment had a high prevalence of low serum albumin and low FFMIs." (PMID 34813604, 2021). "We used age, sex, disease severity, long-term care insurance use, cognitive impairment, and albumin as explanatory variables based on the results of previous studies." (PMID 33374807, 2020). "There was a significant correlation between the extent of BBBd (as measured by the CSF/serum albumin quotient) and the cognitive impairment (as measured by the number of failed tests) (r = 0.53, p = 0.026, n = 14, one-tailed Pearson correlation test)." (PMID 32017808, 2020). "Multiple logistic regression analysis was conducted to investigate the risk factors for UR, including age, body mass index (BMI), serum albumin, cognitive impairment, and activities of daily living (ADL)." (PMID 31192952, 2019). "On the other hand, serum albumin, categorized serum albumin, cognitive impairment, and ADL showed significant differences between the groups (P = .006.003, <.001, and <.001, respectively)." (PMID 31192952, 2019). "CSF Aβ1–42 was lower and CSF tau, CSF p-tau181, CSF p-tau181/Aβ1–42, and CSF albumin index were all higher in those with cognitive impairment." (PMID 28623948, 2017). "Unlike questionnaires such as Mini Nutritional Assessment Short-Form(MNA-SF)that necessitate patient cooperation, CONUT relies solely on three blood indicators (albumin, lymphocytes, and cholesterol), making it feasible for patients with cognitive impairments or those unable to orally consume food." (PMID 41340668, 2025). "The red blood cell distribution width to albumin ratio (RAR) has emerged as a potential biomarker reflecting inflammatory and nutritional status, but its association with cognitive impairment remains unclear." (PMID 40568468, 2025). "It has been found that people who experience cognitive impairment have lower serum albumin levels." (PMID 40678779, 2025).
Cognitive impairment (continued). "Decreased albumin levels could disrupt the oxidant/antioxidant balance and further contribute to cognitive impairment." (PMID 38409895, 2024). "However, a weak trend was noted in women, with elevated albumin levels showing a potential protective effect against cognitive impairment (OR: .72, 95%CI: .41−1.28, P = .262)." (PMID 38409895, 2024). "In our study, we further founded that frailty was linked with a higher burden of comorbidities, an elevated prevalence of emotional and sleep disorders, cognitive impairment, as well as reduced levels of essential biological markers including lymphocytes, hemoglobin, and albumin." (PMID 38424506, 2024). "Rerunning the models without adjustment for chronic diseases, the effect of albumin and cognitive impairment on all-cause (HR = 2.64, 95%CI: 2.04, 3.42) mortality risk was consistent with the primary outcome." (PMID 39114122, 2024). "Frailty is related to the higher score of CCI (τ 0.24), higher incidence of emotional (τ 0.19) and sleep disorders (τ 0.21), cognitive impairment (τ 0.29), higher level of neutrophil count (τ 0.14), lower levels of lymphocytes (τ -0.15), hemoglobin (τ -0.17), and albumin (τ -0.21)." (PMID 38424506, 2024). "Albumin levels were highest in the group with mild cognitive impairment." (PMID 39398776, 2024). "At the same time, a decrease in the body’s albumin content leads to an imbalance between oxidation and antioxidant capacity within the body, accelerating oxidative damage to nerve cells and the development of cognitive impairments." (PMID 39114122, 2024). "Particularly, urinary albumin is a predictor for several kinds of cognitive impairment." (PMID 34415671, 2022). "The levels of ALB and TG in the cognitive impairment group were significantly lower than those in the normal cognitive function group (44.10 [42.70, 45.68] vs. 44.60 [43.30, 45.90], p < 0.001) and (1.28 [0.90, 1.81] vs. 1.38 [0.98, 1.98], p = 0.003), respectively." (PMID 36313027, 2022). "A lower relative α1/albumin intensity (OR: 0.010, 95% CI: 0.000–0.522) was associated with poor outcome at 6 months but not cognitive impairment in patients with SAH expressing Hp2-1." (PMID 35386117, 2022). "A multicenter, multinational study, the FRAILTY‐AVR study, compared seven frailty scales and found that the EFT, which includes chair rises, cognitive impairment, hemoglobin, and serum albumin, outperformed other frailty scales in predicting death and disability at 1 year." (PMID 36193709, 2022). "In the univariable model, cognitively impaired older persons living alone [living alone (+)/cognitive impairment (+) group] were more likely to have a low serum albumin level [crude OR = 3.00, 95% confidence interval (CI) = 1.32 to 6.83] and low FFMI (crude OR = 3.24, 95% CI = 1.34 to 7.83)." (PMID 34813604, 2021). "On the other hand, multivariate analysis showed that age, gender, and categorized serum albumin showed significant differences while no significances were found in cognitive impairment and ADL associated with the occurrence of AP." (PMID 32049822, 2020). "In addition, the expression of ALB, AREG and FCGR2B was notably elevated in hippocampus of DM mice, showing that these proteins may be closely associated with cognition impairment of DM mice." (PMID 40537751, 2025). "Therefore, lower serum albumin levels may reflect malnourishment and potentially contribute to the progression of cognitive impairment." (PMID 38409895, 2024). "Consequently, reduced levels of albumin may interfere with blood supply to the central nervous system, potentially leading to cognitive impairment." (PMID 38409895, 2024). "Many cross-sectional data do not infer causality about whether cognitive impairment results in a lowered serum albumin level or vice versa." (PMID 35160273, 2022).
Cognitive impairment (continued). "There was a time correlation with the tVPA, free concentration and the severity of cognitive impairment, that started at 4,000 mg VPA, and deteriorated as the patient’s albumin dropped from stable 23–26 g/L to 14 g/l." (PMID 40051558, 2025). "Then, age, NYHA (≥3), independence in daily life for the elderly with cognitive impairment (IDL) (≥2), LVEF, eGFR, Ccr, creatinine, NT-proBNP, albumin, DBP, and HR at admission were used as predictors." (PMID 35743806, 2022). "Except for age, female sex, and lower education level, lower level of albumin and elevated AST to ALT ratio correlate with cognitive impairment." (PMID 36313027, 2022). "The degree of cognitive impairment was closely related to ALB, SOD levels and negative clinical symptoms." (PMID 39696133, 2024). "The CSF/blood albumin index was higher in individuals with MCI versus individuals without cognitive impairment (P = 0.005)." (PMID 36506058, 2022). "Our cohort study revealed that the serum concentration of albumin is lower in patients with ESRD with cognitive impairment than in those with ESRD without cognitive impairment." (PMID 34122041, 2021). "Statistical test has found significant differences in age, gender, serum albumin level, and cognitive impairment, between AP and non-AP groups." (PMID 32049822, 2020). "TAA induced cognitive impairment was alleviated by DAPA, as evidenced by reduction by 63% in escape latency of Morris water maze (MWM) test, elevation in fall off period of Rotarod test, and reduced serum ammonia, Liver enzymes, and restore normal serum albumin levels." (PMID 40920270, 2025). "Interestingly, in our study, we observed an inverse correlation between albumin levels and cognitive impairment, specifically in Blacks, but not in other racial/ethnic groups." (PMID 38409895, 2024). "A more recent study of 42 ALS patients and 18 healthy controls also showed a decrease in plasma derived serum albumin in ALS regardless of cognitive impairment, but could not detect disease severity or survival time using albumin at one time-point alone." (PMID 31001186, 2019). "Barthel Index score, MNA-SF score, serum albumin concentrations, hemoglobin levels, and eGFRcys were significantly lower and serum cystatin C levels and percentage of patients with physical frailty and cognitive impairment were higher in patients with SF than in patients without SF." (PMID 36606289, 2022). "Lower levels of albumin, high-density lipoprotein (HDL) and hemoglobin were also noted in the cognitive impairment group." (PMID 36864383, 2023). "Patients with cognitive impairment had significantly smaller HCV, lower hippocampal height, wider choroid fissure and temporal horn than patients without cognitive impairment (p < 0.001); they showed older age and lower albumin level than those without cognitive impairment (p < 0.001)." (PMID 38895693, 2024).
chronic obstructive pulmonary disease (125 papers, 2010 to 2026). A chronic and progressive lung disorder characterized by the loss of elasticity of the bronchial tree and the air sacs, destruction of the air sacs wall, thickening of the bronchial wall, and mucous accumulation in the bronchial tree. "Cox regression analysis revealed that albumin was independently associated with mortality (hazard ratio: 2.48) after adjusting for sex, heart failure, chronic obstructive pulmonary disease (COPD), and CRP levels." (PMID 36267156, 2022). "Patients in group L were older, had a higher incidence of underlying chronic obstructive pulmonary disease, and had higher preoperative levels of hemoglobin and albumin." (PMID 30427854, 2018). "Lower serum albumin levels have also been associated with peripheral vascular disease, chronic obstructive pulmonary disease, cancer and patients using temporary catheters." (PMID 30868008, 2018). "Age, sex, chronic obstructive pulmonary disease as an underlying disease, albumin level, and quinolone and clindamycin use were included in the analysis." (PMID 22571633, 2012). "These conditions may significantly affect neutrophil and albumin levels, potentially confounding the association between the neutrophil-to-albumin ratio and chronic obstructive pulmonary disease." (PMID 40625356, 2025). "For example, the red cell distribution width-to-albumin ratio (RAR) was studied in patients with chronic obstructive pulmonary disease (COPD) and AF, where a higher RAR was associated with significantly increased 28-day mortality​." (PMID 40947484, 2025). "In univariate analysis, age ≥ 80, a male gender, comorbidity with chronic obstructive pulmonary disease (COPD), and lower albumin levels were associated with longer hospital stays in univariate analysis." (PMID 38615301, 2024). "They identified six major contributing variables: age, hospital size, preoperative albumin and hemoglobin levels, type of gastrectomy, and a history of chronic obstructive pulmonary disease." (PMID 41427071, 2025). "The top five important features identified by the SWSFS were chronic obstructive pulmonary disease, preoperative albumin, central venous pressure_T4, cardiopulmonary bypass time, and left ventricular ejection fraction." (PMID 39148090, 2024). "Two independent predictors demonstrated significant statistical association with duration of phLOS: chronic obstructive pulmonary disease (COPD) and preoperative albumin." (PMID 37323526, 2023). "Multivariate analysis revealed predictors, such as albumin level < 3.0 g/dL, HF, and Chronic Obstructive Pulmonary Disease." (PMID 37653832, 2023). "Another study of 164,297 colorectal resection patients discovered that chronic steroid use, overweight, severe chronic obstructive pulmonary disease (COPD), prolonged operation, emergency operations, and low serum albumin levels are strongly linked with postoperative wound disruption." (PMID 35747041, 2022). "The variables were well balanced between the two cohorts, except for the prevalence of chronic obstructive pulmonary disease, the rate of skin soft tissue infections, and albumin levels." (PMID 36082114, 2022). "Of all those infected, a total score was calculated with the use of lymphocyte percentage, lymphocyte count, albumin, Cl, and chronic obstructive pulmonary disease." (PMID 34712677, 2021). "A previous study suggests that patients with chronic obstructive pulmonary disease present increased levels of ischemia-modified albumin as well as oxLDL, due to hypoxia, inflammation, and oxidative stress that these patients experience." (PMID 32884585, 2020). "Compared with TIVA, patients in the VA group were more likely to have histories of chronic obstructive pulmonary disease, lower preoperative total bilirubin and albumin concentrations, and diuretic therapy." (PMID 29070852, 2017).
chronic obstructive pulmonary disease (continued). "Using multivariate modeling, age, chronic obstructive pulmonary disease, cancer, organ dysfunctions and albumin at ICU discharge were the main determinants of 1-year survival." (PMID 26108673, 2015). "Either after adjusting for age and chronic obstructive pulmonary disease or after adjusting for age, chronic obstructive pulmonary disease, C-reactive protein, cholesterol, albumin, pre-albumin, and transferrin, leucine > 174 μM remained an independent predictor of mortality within 6 months." (PMID 35035612, 2022). "COX univariate analysis showed that mortality within 6 months was associated with leucine > 174 μM or <109 μM, age, APACHE II and SOFA scores, chronic obstructive pulmonary disease, and levels of C-reactive protein, cholesterol, albumin, prealbumin, and transferrin." (PMID 35035612, 2022). "Patients with chronic obstructive pulmonary disease had significantly lower albumin." (PMID 32295526, 2020). "Risk factors for severe dengue included chronic obstructive pulmonary disease (COPD), low red blood cell count, low serum albumin, and high fever." (PMID 40692953, 2025). "The relationship between human serum albumin levels and the prognosis of critical care patients with chronic obstructive pulmonary disease (COPD) remains controversial." (PMID 37181348, 2023). "Previous studies demonstrated that PPCs were associated with a series of perioperative risk factors, such as age, smoking, chronic obstructive pulmonary disease (COPD), type of surgery, and serum albumin." (PMID 25821791, 2015). "In this nationally representative study of U.S. adults, a significant association was observed between Life’s Crucial 9 (LC9), the neutrophil-to-albumin ratio (NPAR), and chronic obstructive pulmonary disease (COPD)." (PMID 40625356, 2025). "In the mouse model of chronic obstructive pulmonary disease induced from cigarette smoke exposure (CSE), the liver growth factor (LGF), an albumin-bilirubin complex, exhibited the antifibrotic, antioxidant, and antihypertensive actions at extrahepatic sites." (PMID 35685569, 2022). "Based on the knowledge that chronic obstructive pulmonary disease (COPD) starts in the small airway epithelium, we hypothesized that chronic inflammation modulates peripheral exhaled particle SP-A and albumin levels." (PMID 26656890, 2015). "In this retrospective cohort of 1000 ICU patients with chronic obstructive pulmonary disease (COPD), we assessed the prognostic relevance of inflammatory and nutritional biomarkers, focusing particularly on serum C-reactive protein (CRP), albumin, glucose, creatinine, and lactate levels." (PMID 41010314, 2025). "In addition, in a study of 30-day mortality as an outcome of community-acquired pneumonia, factors such as age, laboratory findings (low albumin, high BUN), and comorbidities (chronic obstructive pulmonary disease, malignant tumor) were reported as predictors." (PMID 38292965, 2023). "BMI: body mass index, urine ACR: ratio of urine albumin to urine creatinine, FEV1: forced expiratory volume in 1 second, FVC: forced vital capacity, FEV1/FVC: ratio of FEV1 to FVC, GOLD stage: Global Initiative for Chronic Obstructive Lung Disease stage, CAT score: COPD Assessment Test score." (PMID 40734883, 2025). "This study aimed to investigate the relationship between nutritional status, mean platelet volume (MPV), C-reactive protein (CRP)-to-albumin ratio (CAR), and mortality in geriatric chronic obstructive pulmonary disease (COPD) patients." (PMID 35070560, 2021).